IL6 (interleukin 6)
Diseases named in the same sentence as IL6 in open-access papers (continued):
Sharing a sentence is not in itself a finding about the gene and the disease.
atherosclerosis (continued). "The effects of gp130 cytokines on these cells (including oncostatin M-[OSM] and IL-6), some of which have been implicated in atherosclerosis, are currently unknown." (PMID 24307759, 2013). "In fact, HIV leads to chronic immune activation and a prothrombotic state, which also features increases in interleukin-1, interleukin-6, and tumor necrosis factor-α which have been implicated in the pathogenesis of atherosclerosis, progression to AIDS, and mortality in HIV-infected persons." (PMID 23394360, 2013). "Consequently, atherosclerotic lesions were smaller and characterized by strongly reduced expression of inflammatory cytokines, such as TNF and IL-6 and also reduced expression of atherosclerosis associated chemokines, such as MCP-1 and RANTES." (PMID 19582157, 2009). "The lower amount of IL-6 and IL-8 found in plaques with high Cav-1 content indeed suggests the importance of Cav-1 in the regulation of pro-inflammatory cascades associated with atherosclerosis." (PMID 18596970, 2008). "IL-6 is a multifunctional cytokine whose presence in the circulation is linked with diverse types of cardiovascular disease and is an independent risk factor for atherosclerosis." (PMID 19936194, 2008). "We assessed whether genetically proxied IL‐6 signaling downregulation is associated with clinical manifestations, imaging biomarkers, and pathological hallmarks of arteriolosclerotic cSVD, using atherosclerosis‐related traits as positive controls." (PMID 41182006, 2025). "Recent studies have shown that certain proteins associated with atherosclerosis, inflammation, and endothelial damage, such as interleukin-6, MCP-3, and osteoprotegerin, accumulate in patients with pore shrinkage syndrome, which may lead to an increased burden of WMHV." (PMID 40280803, 2025). "While these findings may not offer novel perspectives for developing new therapeutic approaches, an ACS risk assessment combining IL-6 and ceramide (d18:1/16:0) presents a unique tool for aiding clinical implementation and decision-making in patients suspected of having atherosclerosis." (PMID 38218768, 2024). "However, a lifetime IL-6 deficiency, as tested in double knockout (ApoE−/−-IL-6−/−) mice, could possibly enhance the development of atherosclerosis." (PMID 37629526, 2023). "Although the mechanism by which IL6 affects AS is unclear, inhibition of IL­6 trans­signalling reduces the incidence of AS, indicating that IL­6 trans­signalling might have a pathogenic role in atherosclerosis." (PMID 37046189, 2023). "Assuming that the severity of atherosclerosis symptoms is associated with the degree of inflammation (active expression of IL-17A), a decreasing percentage of methylation was expected in control subjects, whereas pCAD patients would have the lowest level of methylation, as reported for IL-6 in CAD." (PMID 38132456, 2023). "There is evidence linking RANTES with metabolic syndrome and IL-6, which in turn is directly related to endothelial dysfunction and therefore to an increased risk of HT and cardiovascular events, possibly having an important role in the progression of atherosclerosis." (PMID 35330342, 2022). "Long-term average IL-6 has proven to be a predictor of progression of carotid atherosclerosis, independent of conventional vascular risk factors, suggesting that IL-6 could be a marker and a therapeutic target for accelerated atherosclerosis." (PMID 36362423, 2022). "In asymptomatic individuals, IL-6 levels has shown to be correlated with the degree of left ventricular dysfunction as measured by cardiac magnetic resonance imaging, even after adjusting for demographics, cardiovascular risk factors and markers of subclinical atherosclerosis." (PMID 33709785, 2021).
atherosclerosis (continued). "Future studies may uncover the dual role for monocytes in the development of atherosclerosis and arthritis in ApoE−/− mice and address the effects of ApoE deficiency on joint foam cell formation, IL-6 production and arthritis development in a cell-type specific fashion." (PMID 27287704, 2016). "Pro-inflammatory or innate cytokines released by macrophages including IL-1 and TNF have been implicated in the development of atherosclerosis in mouse models whereas opposing roles of IL-6 have been described that may be dependent on the experimental model used." (PMID 24381786, 2013). "However, sustained IL-6 production is involved in chronic low-level inflammation associated with many diseases, including obesity and insulin resistance, inflammatory bowel diseases, rheumatoid arthritis, sepsis, several forms of cancer and atherosclerosis." (PMID 23782265, 2013). "Moreover, both TNF-α and IL-6 are involved in the inflammatory response occurring in the vascular endothelial cells and promote the initiation and evolution of atherosclerosis by causing endothelial cells to express adhesion molecules and induced endothelial dysfunctions." (PMID 23970974, 2013). "In patients with cardiometabolic risk factors, high IL-6 and TNF-α levels are related to endothelial dysfunction and progression of atherosclerosis, resulting in an increased overall risk for cardiovascular disease." (PMID 41590667, 2026). "Inflammatory pathways involving tumor necrosis factor, interleukin-17, and interleukin-6 appear to promote endothelial activation, oxidative stress, lipid dysfunction, vascular remodeling, and atherosclerosis." (PMID 42232977, 2026). "IL-17 stimulates macrophages to release pro-inflammatory cytokines, such as TNF-α and IL-6, which are involved in the formation and progression of atherosclerosis." (PMID 40276600, 2025). "Inflammatory mediators, including interleukin-6 and high-sensitivity C-reactive protein, play a central role in atherosclerosis and have been shown to correlate with carotid hemodynamic parameters." (PMID 40310398, 2025). "Animal experiments have demonstrated that rutin decreases the expression of inflammatory markers such as IL‐6, IL‐8, and NF‐κB, thereby reducing inflammation and inhibiting the progression of atherosclerosis." (PMID 40634132, 2025). "Pro-inflammatory pathways, including IL-1β/IL-6 signaling, NLRP3 inflammasome activation, and JAK2-mediated thrombo-inflammation, explain its role in atherosclerosis, metabolic dysfunction, and thrombotic risk, highlighting druggable targets for prevention." (PMID 41516113, 2025). "This inflammation leads to an elevation of proinflammatory cytokines, such as interleukin-6 and C-reactive protein, which disrupt endothelial function and promote atherosclerosis." (PMID 40708645, 2025). "Overexpression of NFIA decreased the circulation of inflammatory cytokines, including IL‐6 and TNF‐α, and promoted regression of atherosclerosis in apolipoprotein E‐deficient mice, possibly through the nuclear factor kappa B (NF‐κB) pathway." (PMID 40560736, 2025). "Activation of neutrophils and the release of inflammatory mediators such as TNF-α and interleukin-6 (IL-6) contribute to vascular endothelial injury, exacerbate vascular dysfunction, and promote atherosclerosis." (PMID 41048521, 2025). "In contrast, ligand inhibitors such as ziltivekimab, under investigation for cardiovascular and renal diseases, focus on suppressing IL-6-driven inflammation in conditions like atherosclerosis." (PMID 40066438, 2025). "In the model group, levels of TNF-α and IL-6 were elevated but significantly reduced by hesperidin treatment, indicating its anti-inflammatory role in attenuating atherosclerosis." (PMID 41154096, 2025). "Inflammation drives atherosclerosis growth, with cytokines like interleukin-1, interleukin-6, and tumor necrosis factor sparking the acute-phase reaction and curbing albumin synthesis." (PMID 41536368, 2025).
atherosclerosis (continued). "Elevated levels of pro-inflammatory cytokines such as IL-6 and TNF-α are associated with endothelial dysfunction, atherosclerosis, and plaque formation." (PMID 40184131, 2025). "Ziltivekimab, a novel anti-IL-6 monoclonal antibody, is in development to prevent atherosclerosis in moderate-to-severe patients with CKD." (PMID 39851054, 2025). "The adipose tissue releases adipokines that have a pro-inflammatory (leptin, IL-6) or anti-inflammatory (adiponectin) role in atherosclerosis." (PMID 40137085, 2025). "AOPPs are reported to trigger inflammatory mechanisms, including cytokines (IL-6, IL-1), including macrophages, T lymphocytes, and mast cells, initiating the atherosclerosis process and serving as an early biomarker for atherogenesis." (PMID 40100412, 2025). "In conclusion, there are currently insufficient data to definitively clarify the effect of TCAs on the progression of atherosclerosis through modulation of the IL-6 pathway." (PMID 40006011, 2025). "The results of the CANTOS study indicate that the beneficial effect of Canakinumab on the course of atherosclerosis is, to some extent, attributable to a decrease in IL-6 levels when the drug is administered." (PMID 41303445, 2025). "The most promisingtherapeutic target for the treatment of atherosclerosis among cytokines is IL-6:the antibody ziltivekimab developed against it has shown efficacy and safety in 2phase II clinical trials." (PMID 40160593, 2025). "New treatment options for atherosclerosis prevention are available when one moves upstream in the inflammatory cascade from CRP to IL-6 to IL-1." (PMID 39844544, 2025). "Elevated levels of proinflammatory cytokines like TNF-α, IL-6, and IL-1 contribute to endothelial dysfunction, oxidative stress, and the development of atherosclerosis." (PMID 40376321, 2025). "Given that peel extract down-regulates IL-6 expression in atherosclerosis development, we now examine its modulatory effects across multiple inflammatory models to evaluate systemic anti-inflammatory efficacy." (PMID 41515139, 2025). "Although animal models differ from human disease, the magnitude and trans-model consistency of these effects highlight the therapeutic promise of modulating the AKT/c-FOS/IL-6 axis for IL-6-driven chronic inflammatory disorders such as atherosclerosis." (PMID 41515139, 2025). "Among them, elevated interleukin-6 (IL-6) levels were positively correlated with the atherosclerosis severity and total tau levels in patients with PSP." (PMID 40860217, 2025). "This suggests that the effect of genetically predicted IL‐6 downregulation varies between atherosclerosis‐driven and cSVD‐related stroke subtypes." (PMID 41182006, 2025). "Elevated IL-6 levels have been correlated with increased carotid artery stiffness, a surrogate marker of subclinical atherosclerosis, and a higher incidence of major adverse cardiovascular events (MACE) in HIV-positive populations." (PMID 40787484, 2025). "It is obvious that IL-6 trans-signaling isdominant in atherosclerosis, which reflects the predominantly inflammatory roleof IL-6." (PMID 40160593, 2025). "PPAR-γ agonists suppress pro-inflammatory cytokines (e.g., TNF-α, IL-6) and reduce vascular inflammation, which is a key driver of atherosclerosis." (PMID 40568287, 2025). "In an independent study, DNA methylation of the IL-6 promoter was investigated in a sample of 35 Iranian patients with atherosclerosis versus 30 healthy controls." (PMID 40076974, 2025). "Mechanistically, FC peel extract inhibits AKT phosphorylation, suppresses c-FOS expression and nuclear translocation, reduces IL-6 transcription and inflammation, and thus alleviates atherosclerosis." (PMID 41515139, 2025). "Interleukin-6 (IL-6), a key pro-inflammatory cytokine elevated in atherosclerosis, activates JAK2 signaling and induces the phosphorylation of Beclin 1 (BECN1), a critical protein involved in the initiation of autophagy." (PMID 40244103, 2025).
atherosclerosis (continued). "Lipid markers, including Lp-PLA2 and oxylipins, elucidate lipid metabolism’s contribution to atherosclerosis, while inflammatory biomarkers like TNFα, IL-6, GDF-15, and PTX3 highlight the role of chronic inflammation in CVD progression." (PMID 40244022, 2025). "Anti-inflammatory cytokines (such as interleukin (IL)-5 and IL-13) mitigate atherosclerosis, whereas pro-inflammatory cytokines (such as IL-1, IL-6) quicken the disease’s course." (PMID 40160593, 2025). "IL-6 is a significant biomarker in the context of CVDs, playing a crucial role in the inflammatory response, vascular inflammation, and atherosclerosis." (PMID 40244022, 2025). "Elevated levels of inflammatory mediators, such as TNF-α and IL-6, further damage endothelial function and accelerate the progression of atherosclerosis." (PMID 40672456, 2025). "Inflammatory cytokines IL-1b and IL-6 appear to play a central role in mediating inflammation and subsequently atherosclerosis (i.e. the inflammasome/IL-1/IL‐6 pathway)." (PMID 39988580, 2025). "IL-6 promotes early atherosclerosis by driving chronic inflammation and immune cell recruitment, but its lifelong deficiency exacerbates the disease, highlighting its complex effects." (PMID 40244022, 2025). "It was developed to provide a newoption for the anti-inflammatory treatment of atherosclerosis in patients withchronic kidney disease, as increasing data suggest that the pro-inflammatoryeffects of IL-6 can exacerbate atherosclerosis and thrombosis." (PMID 41209134, 2025). "Key search terms used included “atherosclerosis”, “inflammation”, “biological therapy”, “IL-1β inhibitors”, “IL-6 inhibitors”, and “TNF-α inhibitors”." (PMID 40727466, 2025). "MTX inhibits pro-atherosclerotic cytokines like TNF-α, IL-1, and IL-6, reducing systemic inflammation, which helps mitigate endothelial dysfunction and atherosclerosis progression." (PMID 40376321, 2025). "On the other hand, hypomethylation of inflammatory genes (e.g., TNF-α and IL-6) can drive chronic inflammation, promoting atherosclerosis and plaque instability." (PMID 40416162, 2025). "Another important direction is thestudy of the mechanisms of “switching” from atherogenic to atheroprotectiveaction for cytokines that show a dual role in atherosclerosis: IL-6,TGF-β." (PMID 40160593, 2025). "First, visceral fat is metabolically active and secretes large amounts of inflammatory factors such as TNF-α and IL-6, which induce chronic inflammation and accelerate the progression of atherosclerosis." (PMID 40013161, 2025). "IL-6 promoted the focal occurrence and development of atherosclerosis by inducing this conversion via activating JAK/STAT3 pathway." (PMID 40760703, 2025). "Neutrophils have been shown to play a pivotal role in the inflammatory response of atherosclerosis by secreting substantial amounts of inflammatory mediators, such as IL-1, IL-6, TNF-α, and oxygen free radicals." (PMID 41383228, 2025). "A study involving 37 individuals at heightened risk for atherosclerosis, who were undergoing standard CVD treatment, demonstrated that G. lucidum PsP significantly reduced levels of hs‐CRP, IL‐6, TNF‐α, and MDA." (PMID 40510787, 2025). "Specifically, in hypertensive and prehypertensive patients, inflammatory responses (such as increased levels of IL-6 and TNF-α) are closely associated with the progression of atherosclerosis." (PMID 40034990, 2025). "Chronic inflammation drives the progression of atherosclerosis and other vascular diseases, with inflammatory markers such as C-reactive protein (CRP) and interleukin-6 (IL-6) linked to plaque instability and rupture." (PMID 39777701, 2025).
atherosclerosis (continued). "IL-6 contributes to atherosclerosis by upregulating angiotensin II type 1 receptor expression, while increased binding of angiotensin II in turn increases IL-6 signaling." (PMID 40529825, 2025). "These drugs downregulate inflammatory cytokines, such as IL-6 and TNF-α, which are paradoxically implicated in the pathogenesis of both atherosclerosis and mood disorders." (PMID 40932955, 2025). "Adipose tissue-derived cytokines, including TNF-α and IL-6, promote oxidative stress and endothelial dysfunction, key drivers of atherosclerosis." (PMID 41299285, 2025). "Pro-inflammatory cytokines such as TNF-α and IL-6, which are elevated in arthritis, accelerate endothelial dysfunction and atherosclerosis, creating a bidirectional relationship between arthritis and cardiovascular pathologies." (PMID 41296710, 2025). "GPR41/43 mediates the inhibitory effects of acetate on IL-6 and IL-8, as well as propionate or butyrate on IL-6 production, while HDI activity underlies their suppression of vascular adhesion molecules and PBMC adhesion, mitigating atherosclerosis risk." (PMID 40761338, 2025). "The gathered evidence emphasizes the significance of interleukin (IL)-6 in atherosclerosis and has sparked curiosity about medications that impact IL-6 signaling as a potential treatment option." (PMID 39844544, 2025). "In atherosclerosis, miR-146a exhibits anti-inflammatory properties by inhibiting the NF-κB pathway and regulating cytokine expression, including IL-6, IL-8, IL-17 and TNFα." (PMID 40332077, 2025). "IL-6 is a key pro-inflammatory cytokine that plays a central role in the progression of atherosclerosis by promoting hepatic synthesis of acute-phase reactants, activating endothelial cells, and facilitating leukocyte recruitment into vascular tissue." (PMID 40944256, 2025). "These molecular processes are frequently accompanied by inflammatory responses, resulting in elevated levels of inflammatory markers such as IL-6, further exacerbating endothelial injury and promoting atherosclerosis." (PMID 40395813, 2025). "The innate immune response is activated through Toll-like receptor 4 (TLR4) when LPS levels increase, thus promoting vascular inflammation and atherosclerosis by elevating inflammatory cytokines interleukin-6 (IL-6) and IL-8." (PMID 40421334, 2025). "Beyond CRP, proinflammatory cytokines such as interleukin-1 (IL-1) and interleukin-6 (IL-6) play pivotal roles in the initiation and progression of atherosclerosis and myocardial injury." (PMID 41294894, 2025). "B cells, T cells (including clonally expanded CD4+ cells with heightened proinflammatory and CD8+ cells with cytotoxic properties), granzyme B, TNF-α, IL-6, and TLR 2 and 4 all contributed to the inflammatory processes underlying atherosclerosis." (PMID 40046046, 2025). "Chronic periodontal inflammation contributes to endothelial dysfunction and promotes systemic atherosclerosis via cytokine release (IL-6, CRP) and microbial dissemination." (PMID 41303261, 2025). "The study identified hypomethylation of six CpG sites in the distal IL-6 promoter in the peripheral blood from atherosclerosis patients compared to healthy subjects, which inversely correlated with mRNA expression levels." (PMID 40076974, 2025). "They inhibit the expression of pro-inflammatory cytokines such as IL-6, TNF-α, and C-reactive protein (CRP), which are directly implicated in the pathogenesis of atherosclerosis." (PMID 40807170, 2025). "IL-2, like IL-6, despite its predominant pro-inflammatory functions, can exhibita dual role in the pathogenesis of atherosclerosis." (PMID 40160593, 2025). "Since serum IL‐6 and CRP are predictors of atherosclerosis progression, we found the effects of OO and OA on IL‐6 and CRP were uncertain in our umbrella review." (PMID 41142012, 2025).